IFIT2 (interferon induced protein with tetratricopeptide repeats 2)
Description:
IFN-induced antiviral protein which inhibits expression of viral messenger RNAs lacking 2'-O-methylation of the 5' cap. The ribose 2'-O-methylation would provide a molecular signature to distinguish between self and non-self mRNAs by the host during viral infection. Viruses evolved several ways to evade this restriction system such as encoding their own 2'-O-methylase for their mRNAs or by stealing host cap containing the 2'-O-methylation (cap snatching mechanism). Binds AU-rich viral RNAs, with or without 5' triphosphorylation, RNA-binding is required for antiviral activity. Can promote apoptosis.
Synonyms: IFIT-2; IFI-54K; P54; G10P2; IFI54; ISG54; IFI-54; ISG-54K; ISG-54; cig42; GARG-39; ISG-54 K
Tractability: PROTAC: ubiquitination databases record sites on it; its protein half-life has been measured.
Gene: Protein-coding gene on chromosome 10 (89,283,694 to 89,309,271, forward strand). Ensembl gene ENSG00000119922.
Subcellular location: Cytoplasm; Endoplasmic reticulum
Subcellular location (Human Protein Atlas): Vesicles
Pathways (Reactome):
Immune System: Interferon alpha/beta signaling
Gene Ontology:
Molecular function: protein binding; RNA binding
Biological process: antiviral innate immune response; positive regulation of apoptotic process; response to virus; apoptotic mitochondrial changes; cellular response to cytokine stimulus; defense response to virus
Cellular component: cytoplasm; endoplasmic reticulum; cytosol
Genetic constraint (gnomAD): Loss-of-function variants: 2 observed, 2.34 expected, observed/expected ratio (o/e) 0.85, 90% interval 0.32 to 1.84. That is too few expected variants to judge how well the gene tolerates losing a copy. Missense variants: 488 observed, 584.59 expected, observed/expected ratio (o/e) 0.83, 90% interval 0.77 to 0.9. Synonymous variants: 211 observed, 211.36 expected, observed/expected ratio (o/e) 1, 90% interval 0.89 to 1.12.
Homologues: Orthologues: chimpanzee IFIT2 (99% identical), macaque IFIT2 (97% identical), rabbit IFIT2 (73% identical), pig IFIT2 (72% identical), dog IFIT2 (70% identical), mouse Ifit2 (62% identical), rat Ifit2 (61% identical), tropical clawed frog ifit5l (33% identical), tropical clawed frog ifit5 (30% identical), zebrafish ifit10 (30% identical), zebrafish ifit12 (30% identical), tropical clawed frog ifit1b (30% identical), and 5 more. Paralogues in human: IFIT3 (57% identical), IFIT1 (45% identical), IFIT5 (44% identical), IFIT1B (43% identical).
Diseases named in the same sentence as IFIT2 in open-access papers:
IFIT2 is named in the same sentence as 117 diseases in open-access papers, as found by Europe PMC text mining. Sharing a sentence is not in itself a finding about the gene and the disease. The quoted sentences say what the papers report.
viral infection (79 papers, 2010 to 2025). "Of note, in case of other viral infections such as measles, the RNA-seq analysis of the pharyngeal epithelium of patients revealed that IFIT2 is upregulated and its protein product is associated with response to viral infection." (PMID 35335635, 2022). "IFIT2 can be induced by viral infection, interferon or other pathogen-associated molecular pattern recognition and is involved in inhibiting viral replication and governing apoptosis and antitumor activity." (PMID 36386128, 2022). "To determine the impact of Ifit2 on the outcome of viral infections in vivo, we compared susceptibilities of Ifit2−/− and wt mice to VSV infection, using IFNAR−/− mice as positive controls of enhanced susceptibility." (PMID 22615570, 2012). "Down-regulation of EHMT1 either upon infection or by addition of inhibitors has been reported to activate the Type 1 Interferon signalling pathway via ISGs and Ifit2, which imparts an antiviral response to the host by aiding in clearance of viral infection." (PMID 39509467, 2024). "A model was proposed based on these findings: Before viral infection, IFIT2 enhances translation of cellular mRNAs, including ISGs, to suppress viral infections." (PMID 36558855, 2022). "ISGs such as IFITs have been reported to be important for controlling virus infection in the brain, and we did find increased expression of Ifit1 and Ifit2 mRNA in the brains of INKV-inoculated B6 mice, despite the lack of significant IFN induction." (PMID 35245345, 2022). "Recent studies have shown that IFIT2 primarily limits viral infection and protects mice from severe morbidity and mortality following infection with RABV, lethal VSV, WNV, and Sendai virus (SeV)." (PMID 36325336, 2022). "Overall, these data suggest that IFIT2 has a crucial role in limiting viral infection in specific regions of the brain and in specific cell types." (PMID 36325336, 2022). "Long-range signaling of IFN released from infected neurons at the OB after viral infection of the nasal mucosa upregulated the expression of ISGs (IFIT2, IFIT3, OAS, and MX1) in uninfected brain regions." (PMID 36325336, 2022). "IFIT2 regulates the function of the cell cycle, apoptosis, tumor colonization and viral replication conferring cellular resistance to viral infections and regulating proliferation, apoptosis, and migration of cancer cells." (PMID 33850185, 2021). "SARS-CoV-2 infection of Calu-3 cells, as expected from similar results for SARS-CoV infections, led to induction of a range of genes known to respond to viral infections, such as IFIT2, OAS2, or IFNB1." (PMID 33585804, 2021). "While it has been widely accepted that upregulation of Ifit2 is protective upon several virus infections like Rabies Virus, lethal VSV, WNV, and Sendai virus (SeV) infection, the exact regulatory role is not defined yet." (PMID 33253295, 2020). "Given the dual role played by IFIT2 during viral infection, we asked whether other IFIT proteins may also function to enhance IAV replication." (PMID 40497724, 2025). "Actually, we identified that LCN2, PI3, and SLPI were up-regulated in bacterial infections, and IFI27 and IFIT2 were up-regulated in viral infections in the study, which may be helpful in assisting with the diagnosis of B/V co-infection in children." (PMID 40843077, 2025). "Notably, the mRNA and protein levels of these genes significantly increase following viral infection, with both Ifit2 and Rasd2 exhibiting upregulation across various coronavirus infections." (PMID 40547011, 2025). "Hence, IFIH1, TNFAIP3, IFIT1 and IFIT2 were the common immune response genes regulated by m6A during bacterial or viral infection, or LPS treatment." (PMID 35288544, 2022). "Among these genes, IFIT2 encodes an important IFN-induced protein, one of the key molecules in innate antiviral immune responses, which may contribute to preventing viral infection and pathogenesis in pigs." (PMID 32685145, 2020).
viral infection (continued). "Interestingly, the levels of IFIT2 induction measured after the virus infections were 2.5-fold to 6-fold higher in the IFI44-silenced cells than in the NT-silenced control cells." (PMID 31455651, 2019). "However, genes such as Ifitm10, Ifi203, Ifi205, Ifit1 and Ifit2 showed an upregulated transcription at 6 and 24 h, suggesting that expression of some antiviral genes is regulated by alternative pathways to ensure host-cell survival during viral infections." (PMID 39296294, 2024). "Ifit2 is only expressed at low levels in most cell types under non-pathogenic conditions except for a few myeloid cells, but shows rapid and significant induction upon viral infection." (PMID 33253295, 2020). "While IFITs play a central role in regulating the replication of diverse viral infections, IAV exploits the antiviral activity of both IFIT2 and IFIT3 to enhance replication." (PMID 40497724, 2025). "Children with unexplained fever and low CRP had differentially expressed genes linked to interferon-induced immune responses, including IFIT1, IFIT2, and IFIT3, commonly upregulated during viral infections." (PMID 40806258, 2025). "Our five genes included three genes overexpressed in bacterial infections (LCN2, PI3, and SLPI) and two overexpressed in viral infections (IFI27 and IFIT2)." (PMID 40843077, 2025). "The observed elevation of ISGs, encompassing ISG15, IFI6, IFIT1, IFIT2, IFIT3, IFI44L, and IFITM3, highlights SARS-CoV-2’s ability to activate the host’s interferon response—a critical defence mechanism against viral infection." (PMID 39940816, 2025). "The induction of OAS1, OAS2, and OASL, which, as main sensors for viral infections, explains the induction of numerous interferon-induced proteins (e.g., IFIT1, IFIT2, IFI44, MX1, MX2)." (PMID 39062793, 2024). "Amongst the genes with the most significant difference in expression between the WT and mutant virus infections were antiviral genes (e.g., IRF1, IFIT2, OASL) that exhibited a higher expression in the WT virus infection." (PMID 37243147, 2023). "Previous studies of viral infections have revealed the existence of IFNAR-independent pathways mediating the expression of ISGs, such as IFIT1, IFIT2, IFIT3 and ISG15, all of which were expressed by FVB/N macrophages during priming with M. ulcerans antigens." (PMID 37428812, 2023). "Intriguingly, upregulated IFIT2 and IFIT3 are also involved in the response to viral infection or immune activation and serve as an essential primary barrier to viral infection." (PMID 35232977, 2022). "Interferon induced protein with tetratricopeptide repeats 3 (IFIT3) and interferon induced protein with tetratricopeptide repeats 2 (IFIT2) are both members of IFITs and are highly expressed in the innate immune response of cells to viral infection." (PMID 35187081, 2022). "Downregulation of lincRNA‐EPS during viral infection or genetic knockout of lincRNA‐EPS facilitates PKR‐STAT1 signaling axis induced antiviral genes expression, such as Mx1, Oas2, Ifit2, and Irf7." (PMID 35312140, 2022). "Gene module 3 comprised type I interferon–responsive genes characteristic of stimulated macrophages/monocytes reacting to an active viral infection, such as ISG15, IFIT2, and IRF7." (PMID 35039442, 2022). "We extended our analysis to a range of ISGs that have previously been identified as being regulated directly by virus infection in an IFN-independent manner i.e., IFIT1, IFIT2, IFIT3, ISG15, CXCL10, Mx1 and Mx2." (PMID 30871003, 2019). "As expected, after viral infections, high levels of IFI44 and of IFN-induced protein with tetratricopeptide repeats 2 (IFIT2) (an ISG) were induced." (PMID 31455651, 2019). "The IFIT family includes four canonical human members (IFIT1, IFIT2, IFIT3, and IFIT5) and three mouse members (IFIT1, IFIT2, and IFIT3), which are induced upon simulation with IFN, virus infection, or other PAMP recognition." (PMID 24653722, 2014).
viral infection (continued). "Among the IFN induced genes, IFIT1 and IFIT2 (also named ISG-54 and ISG-56), are known to be highly responsive to viral infection in CNS." (PMID 20927331, 2010). "Previously, it has been reported that in viral infections, m6A often positively correlates with gene expression in immune response pathways, as immune response genes are more active with higher m6A levels, like IFIH1, TNFAIP3, IFIT1 and IFIT2." (PMID 40989927, 2025). "IFIT2 and IFI44L have previously been identified as ISGs during viral infection, supporting our hypothesis that VILMIR may regulate the host interferon response." (PMID 40130878, 2025). "Interestingly, except for IFIT2 in SARS-CoV-2-infected NHBE cells, the expression of the top 10 genes in ACE2high MCF-7 cells exhibited a similar increased trend upon viral infections." (PMID 39625479, 2024). "IFIT1 and IFIT2 (also known as ISG56 and ISG54, respectively) are interferon induced proteins primarily known for their roles in antiviral defense by restricting viral replication and modulating immune responses to combat viral infections." (PMID 39077737, 2024). "Induction of IFIT2 and IFIT3 were observed in hNECs across both lineage infection groups with the strongest signal observed in B/Yamagata-infected cells for IFIT2 with similar amounts of protein detected across all virus infections for IFIT3." (PMID 37766362, 2023). "However, our results show that viral infection or genetic knockout of lincRNA‐EPS facilitates PKR‐STAT1 signaling axis induced antiviral genes such as Mx1, Oas2, Ifit2, and Irf7, while inhibits phosphorylation of TBK1 and IRF3, as well as the IFN‐β induction." (PMID 35312140, 2022). "Our results confirm and extend these observations by showing that the forced expression of IFIT1, IFIT2 or IFIT3 in human fibroblasts completely inhibited the replication of CHIKV and that the individual knock-down of each of these genes facilitated viral infection." (PMID 30959732, 2019). "IFIT (IFN-induced protein with tetratricopeptide repeats (TPRs))-family proteins contain four members in humans, namely IFIT1 (ISG56), IFIT2 (ISG54), IFIT3 (ISG60) and IFIT5 (ISG58), and are induced to high levels in response to IFN signaling and/or viral infections." (PMID 29215570, 2017). "IFIT-1, IFIT-2, IFIT-3, and IFIT-5, which were found to be the most down-regulated genes in LBW newborns, are induced in response to type I and type II IFNs against viral infections." (PMID 23626859, 2013). "IFIT2 is part of a family of proteins that are normally not present in the cell, and are strongly expressed by stimuli such as viral infections." (PMID 23240068, 2012). "A variety of genes such as OAS2, PARP9, OASL, IFIT2, IFI3, CCL8, CXCL10, etc., were highly upregulated and correlated with high viral load, suggesting that innate immune response genes were activated in a viral load dose response manner to control the viral infection." (PMID 37333115, 2023).
COVID-19 (21 papers, 2020 to 2025). A disease caused by infection with severe acute respiratory syndrome coronavirus 2. "Studies have shown that IFIT2 and IFI44L are strongly induced in bronchoalveolar lavage (BAL) cells and peripheral blood mononuclear cells (PBMCs) of COVID-19 patients, leading to enhance antiviral and immune modulatory functions." (PMID 35922752, 2022). "We also identified that the interferon-stimulated genes (ISGs) such as IFIT2, IFI6, and IFI44L were upregulated in COVID-19 patients." (PMID 35922752, 2022). "Given the importance of Ifit2 in providing host immunity, it is the need of an hour to investigate its regulatory role in the lethal HCoV SARS-CoV2 infection which has induced COVID-19 pandemic worldwide and is keeping the entire world in real tenterhooks." (PMID 33253295, 2020). "Moreover, in people with severe COVID-19 the infection reveals a diminished antiviral response marked by the downregulation of antiviral genes such as OAS1, SAMD9L and IFIT2, and suppression of antiviral immune response pathways." (PMID 41168347, 2025). "This would be consistent with a protective effect of upregulated IFIT2 expression in those who developed mild COVID-19 which was not seen in those with moderate/severe disease." (PMID 37261339, 2023). "Genes associated with the IFN pathway, such as IFI27, IFIT1, IFIT2, OASL and OAS3, showed significantly higher expression levels, in particular individuals with long COVID-19 when compared to non-long COVID-19 and the organoid systems infected with the alpha variant." (PMID 40055791, 2025).
colorectal cancer (14 papers, 2017 to 2025). A primary or metastatic malignant neoplasm that affects the colon or rectum. "Previous studies have shown that the AJUBA protein promotes colorectal cancer cell growth by suppressing the JAK1/STAT1/IFIT2 network and activating N-cadherin expression through interaction with Twist in colorectal cancer cells." (PMID 37765273, 2023). "For example, the LIM protein AJUBA promotes the growth of colorectal cancer cells via suppression of the JAK1/STAT1/IFIT2 network and activates N-cadherin expression through interaction with Twist in colorectal cancer cells." (PMID 35898403, 2022). "In colorectal cancer, IFIT2 expression is induced by IRF1, and Wnt/β-catenin signaling, which has antiapoptotic properties, inhibits it." (PMID 36386128, 2022). "Downregulation of IFIT2 expression was observed in colorectal cancer (CRC) tissues compared to normal tissues." (PMID 31921891, 2019). "Exogenous IFIT2 expression decreased cell proliferation and increased apoptosis of colorectal cancer cells." (PMID 29245969, 2017). "Interestingly, the SE-driven lncRNA RP11-569A11.1 reduced cell growth and metastasis by modulating IFIT2 in colorectal cancer." (PMID 37501079, 2023). "Increased expression of IFIT2 has also been reported during induction of apoptosis by various stimuli, such as interferons, cisplatin, lncRNAs, and miRNAs, in oral cancer cells, osteosarcoma cells, gastric cancer cells, and colorectal cancer cells." (PMID 30875792, 2019). "Therefore, reduced expression of IFIT2 might render anti-apoptotic properties to colorectal cancer cells." (PMID 29245969, 2017). "Several research studies have confirmed the ability of IFIT2 to promote the apoptotic death of cancer cells, including OSCC, colorectal cancer, leukemia, osteosarcoma, and hepatocellular carcinoma." (PMID 31921891, 2019). "On the contrary, research into the IFN-γ/JAK/STAT1/IFIT2 pro-apoptotic pathway has uncovered that AJUBA, with increased expression in colorectal cancers, may induce tumor progression by specifically binding to the FERM domain of JAK1." (PMID 40909948, 2025). "To create an endogenous type I IFN reporter, we chose the colorectal cancer cell line HCT116, which is highly efficient for CRISPR-based gene editing, and surveyed IFNα induction of canonical type I IFN target genes (IFIT1, IFIT2, IFIT3, IFI27, IRF7, OASL, RSAD2)." (PMID 38358346, 2024). "And HSPH1 was highly expressed in different tumors, such as colorectal cancer, B-cell lymphoma, melanoma and esophageal squamous cell carcinoma, while NAA25 knockdown could upregulate IFIT2 and NDRG1 expression and downregulate HSPH1 expression." (PMID 35096568, 2021). "In this study, we identified IFIT1 and IFIT2 as genes down-regulated by Wnt signaling in colorectal cancer (CRC) cells, and clarified that inhibition of IFIT2 may play a role in the proliferation and anti-apoptotic properties of CRC cells." (PMID 29245969, 2017).